RNF2 (ring finger protein 2)
Diseases named in the same sentence as RNF2 in open-access papers (continued):
Sharing a sentence is not in itself a finding about the gene and the disease.
Hepatitis (1 paper, 2026). Inflammation of the liver. "For instance, hepatitis C virus (HCV) infection leads to the degradation of RNF2, resulting in a reduction of H2AK119 monoubiquitination levels in host cells, thereby inducing the expression of HOX genes and facilitating viral propagation." (PMID 41499632, 2026).
Hirschsprung disease (1 paper, 2022). Hirschsprung disease (HSCR) is a congenital intestinal motility disorder that is characterized by signs of intestinal obstruction due to the presence of an aganglionic segment of variable extent in the terminal part of the colon. "This clearly shows that the rnf2 gene plays an important role in ENS development and highlights it as a novel candidate gene in Hirschsprung’s disease." (PMID 36117635, 2022).
ischemia (1 paper, 2024). A hypoperfusion of the BLOOD through an organ or tissue caused by a PATHOLOGIC CONSTRICTION or obstruction of its BLOOD VESSELS, or an absence of BLOOD CIRCULATION. "In this study, we provided evidences for the first time that RNF2 was significantly upregulated in human and rat ischemia brain and RNF2 overexpression alleviated brain injury induced by MCAO." (PMID 39614674, 2024). "In addition, most of mCherry‐positive cells are NeuN‐positive neurons, but also existed in some NeuN‐negative cells, suggesting that AAV‐RNF2 leads to a wide expression of RNF2 in the ischemia brain." (PMID 39614674, 2024). "Together, these data show that RNF2 alleviates ischemia‐induced neuronal apoptosis." (PMID 39614674, 2024).
latent infection (1 paper, 2024). "CMV latent infection associated hyper-methylated CpG sites are enriched in PcG proteins including RNF2, EZH2, KDM2B and JARID2." (PMID 39360678, 2024).
learning disability (1 paper, 2025). A group of disorders that affect a person's ability to learn or process specific types of information which is in contrast to his/her apparent level of intellect. "Individual 6, who carries a truncating RNF2 variant, was diagnosed with a learning disability." (PMID 40831499, 2025).
liver steatosis (1 paper, 2025). "Our data indicated that RNF2 knockdown alleviated liver injury and hepatic steatosis in ALD model mice." (PMID 40384855, 2025). "The study found that hepatic-specific RNF2 knockdown attenuated EtOH-induced liver steatosis and inflammation." (PMID 40384855, 2025). "In summary, RNF2 knockdown reduced hepatic steatosis and inflammation, and attenuated liver injury in ALD mice." (PMID 40384855, 2025). "Similarly, RNF2 was also increased in the livers of ALD model mice, and this change was accompanied by liver steatosis and injury." (PMID 40384855, 2025).
luminal breast cancer (1 paper, 2023).
metabolic dysfunction-associated steatotic liver disease (1 paper, 2025). Metabolic dysfunction-associated steatotic liver disease (MASLD, formerly known as nonalcoholic fatty liver disease or NAFLD) is a type of liver disease that is not caused by alcohol. "Although our study focused on ALD, the role of RNF2 in lipid metabolism and inflammation suggests its potential relevance in Metabolic Dysfunction-Associated Steatotic Liver Disease (MASLD)." (PMID 40384855, 2025).
metastatic melanoma (1 paper, 2018). A melanoma that has spread from its primary site to another anatomic site. "Such a beneficial effect of high RNF2 expression found for both the primary and metastatic melanomas is much stronger in the case of primary lesions but is clearly observed also if one analyses both the types of the lesions as one group." (PMID 29707138, 2018).
renal fibrosis (1 paper, 2018). A final common manifestation of a wide variety of chronic kidney diseases characterized by glomerulosclerosis and tubulointerstitial fibrosis. "Rnf2 was increased in the diabetic rat kidney and may play roles in the development of type 1 diabetes-induced renal fibrosis." (PMID 30200873, 2018).
teratocarcinoma (1 paper, 2012). A germ cell tumor characterized by the presence of an embryonal carcinoma component and a teratoma component. "By shRNA mediated knockdown, DNA microarray expression analysis and ChIP analysis, we show that a number of genes are co-regulated by REST and RNF2 in human teratocarcinoma NT2-D1 cells." (PMID 22396653, 2012). "Here we present evidence for an interaction between the transcription factor REST, PRC1, and PRC2 and show that RNF2 and REST co-regulate a number of neuronal genes in human teratocarcinoma cells (NT2-D1)." (PMID 22396653, 2012).
cancer (43 papers, 2011 to 2025). A tumor composed of atypical neoplastic, often pleomorphic cells that invade other tissues. "RNF2 missense variants are enriched in both NDDs and cancer, underscoring their pathogenic potential." (PMID 40831499, 2025). "RNF2 is upregulated in many kinds of tumors, and elevated RNF2 expression is associated with a poor prognosis in certain cancers." (PMID 33346749, 2020). "Overexpression of RNF2 was observed in 44.0% of UCBs and was found to significantly associate with shortened overall and cancer-specific survival (P < 0.001)." (PMID 26869491, 2016). "Additionally, RNF2 missense variants are highly enriched in the COSMIC cancer database, and, like NDDs, it predominantly features missense rather than truncating mutations, highlighting pathogenic mechanisms of RNF2 missense variants yet to be revealed." (PMID 40831499, 2025). "RNF2 has been implicated in a variety of normal physiological processes as well as pathological conditions, such as embryonic development, immune surveillance, cancer metastasis, and inflammation." (PMID 39614674, 2024). "Several studies have demonstrated that the expression of RNF2, a PcG protein, is associated with the tumor grade and prognosis, and could serve as a prognostic biomarker and therapeutic target in certain cancer types." (PMID 33346749, 2020). "To initially assess whether PRC1 components are altered in cancer, we examined the mutational frequencies of the histone H2A mono-ubiquitin ligases RNF2 (encoding RING1B) and RING1, the cPRC1 genes, and the core PRC1-encoding genes in large-scale genomic data sets from cancer patients." (PMID 30139998, 2018). "More broadly, our results highlight the role of RNF2 in maintaining lineage fidelity and demonstrate the utility of developmental models for uncovering chromatin-based mechanisms relevant to cancer biology." (PMID 40831499, 2025). "RNF2 is a member of the PcG family of proteins, which has been recognized to play crucial roles in cancer development." (PMID 39614674, 2024). "RNF2 has been found to be highly expressed in several human cancers and to be related to poor survival." (PMID 36271315, 2023). "RNF2 is highly expressed in multiple cancer types and contribute to tumor proliferation, metastasis, and drug resistance." (PMID 37037816, 2023). "CBX8, BMI1, and RNF2 are interaction proteins that maintain transcriptional repression of hundreds of cancer growth and signaling-related genes." (PMID 35813444, 2022). "This body of evidence validated that downregulation of RNF2 is accountable for the anti-cancer effects of miR-149." (PMID 35129056, 2022). "Previous studies have shown that RNF2 was abnormally expressed in many types of cancer including HCC." (PMID 33816485, 2021). "Despite the role RNF2 plays in biological processes in cancers via its diverse mechanisms, it highlights the potential oncogenic activity of RNF2 on NSCLC." (PMID 32170141, 2020). "For instance, H2A ubiquitin ligase RNF2/RING1b and H2B deubiquitinase USP22 are associated with poor prognosis in numerous cancers." (PMID 29934362, 2018).
cancer (continued). "It has been reported that RNF2 has very low expression in normal tissues, but has high expression in certain cancer types." (PMID 28029659, 2017). "RNF2 has been considered to be a prognostic biomarker and potential therapeutic target for these cancer types." (PMID 28029659, 2017). "Notably, several genes identified in our CRISPR screen, including ARID1A, PSIP1, RNF2, UBE2D and MEN1, were previously associated with chemoresistance in various cancer types, reinforcing the biological relevance of our findings." (PMID 40583060, 2025). "The pathogenicity of RNF2 missense variants is also supported by the enrichment of RNF2 missense variants in the COSMIC cancer database, as opposed to termination variants." (PMID 40831499, 2025). "RNF2 (also known as ding, Ring1B, or Ring2) is a member of the polycomb group (PcG) of proteins, which form chromatin‐modifying complexes essential for embryonic development and stem cell renewal, which are commonly deregulated in cancer." (PMID 39614674, 2024). "Mechanistically, RNA pulldown and RIP revealed that PRR7-AS1 may bind RNF2 to play a cancer-promoting role." (PMID 38033505, 2023). "Furthermore, this study revealed that knockdown of MTUS1 reversed the regulatory effect of PRR7-AS1 and RNF2 on OS cells behaviors, validating the anti-cancer role of MTUS1 in OS." (PMID 38033505, 2023). "Other factors, such as the embryonic transcription factor double homeobox 4 (DUX4), lymphocyte adapter protein (LNK), the ubiquitin ligases RING finger protein 2 (RNF2), and the protein kinase D2 (PKD2) have been implicated in impaired IFN and MHC-I signaling in different cancers." (PMID 36551849, 2022). "It has been reported that RNF2 was expressed in very low levels in normal tissues but was highly expressed in certain cancer types and considered to be a prognostic biomarker and potential therapeutic target for various cancers." (PMID 34224728, 2021). "In recent years, a growing amount of evidence suggests that RNF2 may play an important role in multiple pathological processes involved in cancer." (PMID 33816485, 2021). "However, the precise mechanism by which RNF2 exerts its effects on human malignant tumors largely remains elusive." (PMID 27911266, 2017). "Similarly, genes that become hypomethylated by functional depletion of CBX4 or RNF2, or by joint knockdown of EED and RNF2, are enriched for those that commonly become hypermethylated in human cancers." (PMID 25071008, 2014). "From this perspective, we propose that RNF2 might be an oncogene in human cancers." (PMID 36271315, 2023). "Studies have depicted that RNF2, BMI1, TRIM37, and other ubiquitinating genes were related to cancer progression." (PMID 37980168, 2023). "Taken together, our findings provide strong evidence that NPM, E3 ligase RNF2, and GADD45a directly and functionally control powerful RAS effector networks that are vital in multiple cancer processes." (PMID 34224728, 2021). "The concomitant activation of polycomb ubiquitin ligases RNF2 and deubiquitinase USP22 is significant during cancer progression because USP22 activation allows transcriptional up-regulation of cell cycle related genes." (PMID 29934362, 2018). "However, some clinical reports suggest that the RNF2 and HOX proteins are highly expressed in cancer tissues." (PMID 39329491, 2024). "In the remaining 71 informative cancers without RNF2 amplification, 46 (64.8%) cases showed normal expression of RNF2, while 25 (35.2%) cases showed overexpression of RNF2." (PMID 26869491, 2016). "For example, HAX1, RNF2, and CAV1 interact with ABCB1, and these proteins are also prioritized in the top 5 candidate list in VCR study using ProteinRank and involved in chemoresistance in various carcinoma cells." (PMID 26039373, 2015).
cancer (continued). "Consistent with the intolerance of RNF2 to LOF, NDD or cancer substitutions did not exhibit the most pathogenic VES of −20.00, highlighting the contribution of hypomorphic RNF2 missense variants to the pathology of NDDs and cancer." (PMID 40831499, 2025). "Furthermore, studies on NPM-mediated suppression of RNF2 expression and role of RASSF10 on cell cycle regulation in presence of chemotherapeutic drugs might help in designing novel cancer treatment strategies." (PMID 34224728, 2021).
tumor (42 papers, 2008 to 2025). "High RNF2 expression is associated with poor overall survival and promotes tumor cell growth and metastasis in HCC." (PMID 36262473, 2022). "RNF2 expression was associated with clinicopathologic features such as the tumor differentiation status, TNM stage and Duke’s stage." (PMID 33346749, 2020). "In summary, our study revealed that RNF2 expression was greater in CRC tumor tissues than in adjacent normal tissues, and was associated with the clinicopathologic features and prognoses of CRC patients." (PMID 33346749, 2020). "Here, we examined the expression of RNF2 in CRC tumor tissues and evaluated its association with clinicopathologic features and patients’ prognoses." (PMID 33346749, 2020). "When we analyzed the association between RNF2 levels and clinicopathologic characteristics, we observed that RNF2 positivity was associated with a significantly worse tumor differentiation status, tumor-node-metastasis (TNM) stage and Duke’s stage." (PMID 33346749, 2020). "Kaplan-Meier analysis of tumor samples revealed that high RNF2 expression with concurrent low SIK1 expression is associated with poor overall survival." (PMID 27911266, 2017). "In addition, we evaluated a potential association between RNF2 expression and tumor clinicopathologic features in UCBs." (PMID 26869491, 2016). "Simultaneously, as a core component of PRC1, RNF2 can suppress the expression of tumor suppressor genes through histone modifications, thereby further driving tumor development." (PMID 40809844, 2025). "Their research revealed that miR-149 exhibited low expression levels, while DNMT3B and ring finger protein 2 (RNF2) displayed high expression levels within ESCC tumor samples." (PMID 37705098, 2023). "Studies have shown that the expression of RNF2 is related to the decrease in cytotoxicity of tumor infiltrating immune cells." (PMID 36553670, 2022). "miR-149 was poorly expressed whereas DNA methyltransferase 3 beta (DNMT3B) and ring finger protein 2 (RNF2) were abundantly expressed in ESCC tumor samples." (PMID 35129056, 2022). "Other studies suggest that RNF2 allows ubiquitination of H2A and downregulation of RNF2, which inhibits tumor proliferation in PDAC in vitro." (PMID 34198989, 2021). "Since PcG proteins transcriptionally repress gene expression, we concentrated on several tumor suppressors that were upregulated in RNF2-knockdown cells." (PMID 33346749, 2020). "In a univariate analysis, RNF2 expression, tumor cell differentiation, the Duke’s stage and the TNM stage were all associated with the CRC prognosis." (PMID 33346749, 2020). "Immunohistochemistry was used to examine RNF2 expression in tissue microarrays containing 313 paired CRC tumor tissues and adjacent normal tissues." (PMID 33346749, 2020). "RNF2 protein levels were noticeably greater in CRC tumor tissues than in adjacent normal tissues (H-scores: 64.40±56.14 and 43.54±66.38, respectively)." (PMID 33346749, 2020). "Considering that PcG proteins repress gene transcription, we mostly concentrated on tumor suppressors that were upregulated in RNF2-knockdown cells." (PMID 33346749, 2020). "We first evaluated RNF2 expression in 313 paired CRC tumor tissues and adjacent normal tissues, and observed that RNF2 was markedly upregulated in CRC tumor tissues." (PMID 33346749, 2020). "On the contrary, RNF2, a predicted target gene of tumor-suppressive miRNA cfa-miR-149, was upregulated in tumor tissues." (PMID 31569550, 2019). "Based on the phenomenon that RNF2 exert an oncogenic function and can suppress gene expression, we mainly focused on several tumor suppressor genes." (PMID 28029659, 2017). "The expression level of TXNIP was also examined by IHC in RNF2 knockdown DU145 xenograft tumor tissues, and results showed that RNF2 knockdown group had increased TXNIP level than the control group." (PMID 28029659, 2017). "The staining score of RNF2 was higher in HCC tissues (4.46 ± 0.13) than in non-tumor tissues (3.02 ± 0.23) (P < 0.009)." (PMID 27911266, 2017).